AFP (alpha fetoprotein)
Diseases named in the same sentence as AFP in open-access papers (continued):
Sharing a sentence is not in itself a finding about the gene and the disease.
liver cancer (continued). "We performed univariate analysis of risk factors for HCC postoperative recurrence and survival, including age, gender, HBsAg-positive status, family history of liver cancer, degree of fibrosis, tumor volume, tumor diameter, and AFP level." (PMID 23981851, 2013). "It has been reported that the use of ultrasound in combination with alpha-fetoprotein testing has specificity of above 90% in confirming clinical impression of liver cancer in the Sahel region." (PMID 24098724, 2013). "Liver function and AFP values of 25 patients with malignant liver tumors before and after treatment with Radiofrequency Ablation combined with Low-Frequency Ultrasound Radiation with Microbubbles." (PMID 23326418, 2013). "Conversely, because AFP levels in blood are high in only approximately 60% of liver cancer patients and other benign diseases (hepatitis, liver cirrhosis), there is a limitation in using AFP alone as an HCC marker in blood." (PMID 23717429, 2013). "In patients with cirrhosis or chronic hepatitis B or hepatitis C infections, AFP is the most important serum marker to predict liver cancer occurrence." (PMID 23981851, 2013). "The cytopathic effects of Ad.SPDD-HCCS1 and Ad.SPDD-HCCS1HA were equal to that of ZD55-HCCS1 in the AFP positive liver cancer cell lines Huh-7 and HepG2." (PMID 22040050, 2011). "AFP promoter was used to control the anti-tumor gene cytosine deaminase and cytosine deaminase specially expressed in liver cancer cells." (PMID 22040050, 2011). "AFP-producing ovarian cancer and gastric cancer have also been reported, whereas AFP-producing liver cancer is rare." (PMID 21554678, 2011). "In regard to tumor markers, cases of AFP-producing liver cancer presenting with elevated serum CEA or HCG levels have been reported." (PMID 21554678, 2011). "The adenovirus with the key replicative gene E1A under the control of AFP promoter can specially replicate in AFP positive liver cancer cell lines." (PMID 22040050, 2011). "In relation to its pathological significance, serum AFP is useful as a tumor marker in patients with liver cancer." (PMID 21554678, 2011). "α-fetoprotein (AFP) is an established marker of liver cancer, and it is present at increased levels in the serum of approximately 75% of all liver cancer patients." (PMID 22040050, 2011). "In regard to the pathological significance of this protein in adults, serum AFP is often elevated in patients with liver cancer or gonadal germ cell tumors, such as yolk sac tumor." (PMID 21554678, 2011). "The progression of liver disease to liver cancer is primarily monitored by serum levels of the oncofetal glycoprotein, alpha-fetoprotein (AFP), or the core fucosylated glycoform of AFP, AFP-L3." (PMID 20811639, 2010). "The NCSP recommends liver cancer screening every six months for men and women aged 40 years and older who are at high risk for liver cancer such as liver cirrhosis, HBsAg positive, or anti-HCV positive, with alpha-fetoprotein (AFP) and ultrasonography." (PMID 19930718, 2009). "The precise elucidation of the biological effect of AFP will help to better understand the regulatory mechanism of immune surveillance in liver cancer." (PMID 16080799, 2005). "The higher level of AFP in the serum of liver cancer subject has been considered to be the reason of tumor development rather than merely the concomitant oncofetal protein." (PMID 16080799, 2005). "The biomarker alpha-fetoprotein holds a dominant position in liver cancer detection." (PMID 41496090, 2026). "Thirty clinical liver cancer samples and multi-omics databases were collected; the expression of AFP, GMR-related proteins, pyruvate kinase M2 (PKM2), and the PI3K/AKT signalling pathway-associated proteins were assessed using immunohistochemistry (IHC) or Western blotting." (PMID 42244055, 2026).
liver cancer (continued). "Besides, the model outperformed the traditional liver cancer biomarker AFP and showed changes in methylation signals before and after surgery, suggesting a possible role in perioperative monitoring." (PMID 42145083, 2026). "Furthermore, the observed increase in the levels of in alpha-fetoprotein (a marker for liver cancer) with unaltered albumin levels (a marker for healthy liver function) suggested a potential shift towards a more malignant state." (PMID 41928920, 2026). "For serum AFP, AFP-L3% and PIVKA-II detection, the results of this study suggested that the diagnostic models GALAD, ASAP, GALAD-C and C-GALAD are recommended preferentially in the diagnosis of liver cancers (including HCC, CCA and their early stages)." (PMID 40708828, 2025). "Research is ongoing to target AFP in patients with liver cancer." (PMID 40430002, 2025). "Notably, PDX models generated with Liver ECM displayed higher expression of liver cancer-specific markers AFP and ALB, compared to PDX models with Matrigel, indicating enhanced tumor progression by Liver ECM." (PMID 40852642, 2025). "Furthermore, incorporating the detection of AST and ALT into the screening process for AFP can significantly enhance the detection capacity for liver cancer." (PMID 41142312, 2025). "Immunofluorescence staining showed higher protein expression of the liver cancer differentiation marker AFP in the xenografts generated with Liver ECM (4 and 6 mg/ml) than in those with Matrigel, while the level of the proliferation marker Ki67 was comparable between these groups." (PMID 40852642, 2025). "Alpha fetoprotein, Resistance, promotion and Cell survival may be closely related to biomarkers and drug resistance in liver cancer immunotherapy." (PMID 40276056, 2025). "However, recent studies have indicated that the role of AFP extends far beyond its traditional characterization as a liver cancer marker." (PMID 40430002, 2025). "Raised AFP often can act as an early sign of liver cancer in individuals with liver disease." (PMID 40870868, 2025). "Alpha-fetoprotein (AFP) is an established biomarker for liver cancer, but its role in gastric cancer (GC) remains unclear." (PMID 40485723, 2025). "Clinical translational analysis revealed that Csrp2 demonstrates superior diagnostic efficacy (AUC >0.8) in HCC tissues compared to conventional biomarker AFP, with its peripheral blood detection technology showing promise for non-invasive early screening of liver cancer." (PMID 41323394, 2025). "Additionally, combining AFP vaccination with immune checkpoint inhibitors enhanced the immune response, ultimately leading to the suppression of liver cancer growth in mice." (PMID 40430002, 2025). "AFP is often used in clinical settings to diagnose and monitor liver cancer progression." (PMID 39996991, 2025). "Examples include alpha-fetoprotein (AFP) for liver cancer, cancer antigen 125 (CA125) for ovarian cancer, carcinoembryonic antigen (CEA) for colon cancer, prostate-specific antigen (PSA) for prostate cancer, and carbohydrate antigen 19-9 (CA19-9) for gastrointestinal and pancreatic cancers." (PMID 40868286, 2025). "Furthermore, MRD positivity was revealed to be an independent prognostic factor for previously identified risk factors such as high alpha-fetoprotein (AFP) levels, microscopic vascular invasion, and Barcelona Clinic Liver Cancer (BCLC) stage." (PMID 39920551, 2025). "AFP, a commonly used tumor marker, is particularly significant in the diagnosis of liver cancer." (PMID 40458724, 2025). "The synergistic effect of both significantly boosts AFP detection signals while reducing background noise, resulting in a substantial improvement in detection sensitivity and specificity, particularly for early-stage liver cancer screening." (PMID 39722094, 2024).
liver cancer (continued). "In addition, we compared the ability of LUC7L3 with the existing liver cancer biomarkers AFP and DCP to stratify HCC patients, showing that they had similar abilities in predicting the prognosis of patients with full-stage HCC (Gao’s cohort and Xing’s cohort)." (PMID 38785515, 2024). "Additionally, AFP elevation can occur in benign liver diseases and embryonic tumors, posing challenges in early liver cancer identification." (PMID 39432605, 2024). "Furthermore, AFP also suppresses the proliferation and cytotoxicity of T cells, thereby attenuating their response to liver cancer cells." (PMID 38660138, 2024). "Similarly, AFP levels were detected in the liver cancer tissue at high levels but were detected at lower levels in the liver of miR-10a/b mimic-injected diabetic mice and healthy mice." (PMID 38396943, 2024). "Although the viral load differences were not statistically significant, the elevated AFP levels suggest a greater risk of liver cancer in these patients." (PMID 39599836, 2024). "Previous study suggested that a combination with AFP could improve the sensitivity and specificity of ctDNA for predicting prognosis of patients with liver cancer." (PMID 38183515, 2024). "This marker is the cornerstone that paves the way for the development of further diagnostic markers and therapeutic targets for AFP-negative liver cancer patients." (PMID 38835390, 2024). "The results revealed that patients with BMI ≤ 20.425 (the dose limitation of V15 < 34.90%), ECOG = 1–2 (<33.67%), Alpha-fetoprotein (AFP) ≥ 400 ng/ml (<33.20%), Barcelona clinic liver cancer (BCLC) = C (<39.45%), HBV -positive (<34.90%) and hepatic fibrosis (<34.90%) required a lower dose of V15." (PMID 38376811, 2024). "AFP, primarily produced by the liver and yolk sac during fetal development, exhibits elevated levels in liver cancer due to various factors, including the release of AFP directly from the cancer cells or by the disruption of normal liver cellular function and, thereby, the leakage of AFP." (PMID 38921027, 2024). "Therefore, expression of phosphorylated mTOR (p-mTOR) signifies and increased tumor grade, and elevated alpha-fetoprotein (AFP) indicates enhanced metastasis, invasion, and proliferation of liver cancer cells." (PMID 39349424, 2024). "Therefore, investigating the mechanisms governing the interaction between AFP and immune evasion of liver cancer holds promise for the discovery of novel approaches for immunotherapy in HCC." (PMID 38660138, 2024). "Consequently, further research is necessary to clarify the relationship between AFP levels and immune benefits in advanced liver cancer." (PMID 39038010, 2024). "The AASLD recommends the use of serum AFP combined with ultrasound for liver cancer screening." (PMID 39161764, 2024). "Other studies indicate that the longer OS may be because of earlier liver cancer detection since more women undergo regular ultrasound and α-fetoprotein (AFP) tests, and therefore have better treatment results." (PMID 38918710, 2024). "Hence, the quantitative analysis of AFP concentration is crucial for early clinical diagnosis of liver cancer and long-term treatment." (PMID 39065385, 2024). "We also identified a proliferative cluster, which mainly consisted of proliferating T cells and a large cluster of HCC cancer cells (40%) expressing both genes associated with normal liver function (ALB, HP, FGA, FGB) and liver cancer (AFP, SPINK1, GPC3, AKR1C1)." (PMID 38030622, 2023). "The AFP-modified immune cell vaccination or peptide vaccine demonstrated specific antitumor immunity against AFP-positive tumor cells, laying a solid basis for liver cancer immunotherapy." (PMID 37377916, 2023). "AFP is one of the most widely used biomarker for liver cancer." (PMID 37821948, 2023).
liver cancer (continued). "Alpha-fetoprotein (AFP), the most specific marker for liver cancer, is traditionally detected by many analytical techniques, including radioimmunoassay (RIA), chemiluminescence immunoassay (CLIA), enzyme-linked immunosorbent assay (ELISA), time-resolved fluorescence immunoassay (TRFIA), etc.." (PMID 37175021, 2023). "Additionally, using logistic regression, we demonstrated that CDCA8 not only exhibited marked differential regulation in liver cancer and adjacent tissues, but also showed differences in various subgroups, such as, T stage, PS, TS, HG, and AFP." (PMID 36855818, 2023). "Additionally, in the early stages of liver cancer, the concentration of AFP is often low, so signal amplification strategies are commonly employed to enhance detection sensitivity." (PMID 37836778, 2023). "In-depth exploration of the relationship between AFP and phagocytosis of macrophages, and targeted intervention of AFP could provide new therapeutic hope for patients with liver cancer." (PMID 36911723, 2023). "Although most patients with liver cancer have high serum AFP levels, liver cancer is not the only cause of elevated AFP, as abnormalities in this indicator can also be detected in patients with lung cancer or pancreatic cancer and in pregnant women." (PMID 36990999, 2023). "Therefore, developing a label-free, safe, rapid, steady, and economical approach to detecting AFP concentrations in serum for large-scale screening of liver cancer is of great importance." (PMID 37175021, 2023). "In sum, these integrated analyses with clinical data support the future use of CmPn members’ expression data, along with AFP, as potential prognostic biomarkers for distinguishing between primary subtypes of liver cancer and evaluating tumor recurrence in patients." (PMID 36980321, 2023). "The median AFP level and maximal tumor size were 98.96 (10.93–2786.89) ng/mL and 8.0 (4.9–11.5) cm, respectively, and the patients were all classified as having Barcelona Clinic Liver Cancer stage C HCC." (PMID 38132371, 2023). "Additionally, AFP has been shown to drive fetal and adult liver cancer development, potentiating FGFR and transmembrane mucin signaling." (PMID 36834607, 2023). "The modified attenuated S. typhimurium could express AFP specific to liver cancer and then activate T cells to kill and clear the tumor." (PMID 37765183, 2023). "After the initiation of programmed cell death-1 (PD-1) inhibitor therapy, the patients with decreased levels of serum-specific tumor markers (SSTMs) had significantly better OS and PFS than those with increased levels of SSTMs, and AFP was used in five cases of liver cancer." (PMID 37190231, 2023). "The rapid and convenient determination of AFP levels is essential for early liver cancer diagnoses." (PMID 37175021, 2023). "Therefore, all patients with acute porphyria over the age of 50 years should undergo lifelong screening for liver cancer, liver ultrasound, and serum alpha-fetoprotein measurement every 6 to 12 months." (PMID 38115298, 2023). "As we all know, alpha-fetoprotein (AFP) is very important for the diagnosis of liver cancer." (PMID 37686101, 2023). "Silencing the expression of AFP induces apoptosis of HepG2 hepatic cancer cells." (PMID 36768863, 2023). "In addition to being a predictor, AFP has also been considered for immunotherapy and defining molecular classes of liver cancer." (PMID 37700838, 2023). "Thus, early-stage liver cancer detection is of great significance for successful treatment, and in this study, we mainly studied the quantitative molecular diagnosis of alpha-fetoprotein (AFP)." (PMID 37887110, 2023). "Studies referring to liver cancer and AFP detection methods were excluded." (PMID 37781207, 2023). "Liver Doppler ultrasound and AFP are simple and easy methods to screen liver cancer." (PMID 37035138, 2023).
liver cancer (continued). "Thus, the development of high sensitivity and selectivity, rapid, accurate, and low-cost methods for detecting AFP is of the great interest for early cancer diagnosis and monitoring of liver cancer after long-term treatment." (PMID 37284243, 2023). "Hence, an electrochemical aptasensor was developed by modifying a screen-printed carbon electrode with 2D MoSe2/WSe2 to detect a biomarker for primary liver cancer named prime alpha-fetoprotein (AFP); this was able to achieve a detection limit of 0.65 pg·mL−1." (PMID 37232930, 2023). "However, when homogeneous electrochemical aptamer sensors are used for AFP analysis in serum, they still face challenges such as complex matrix and low concentration of AFP in early-stage liver cancer." (PMID 37836778, 2023). "AFP is a routine screening marker for patients with liver cancer." (PMID 37519810, 2023). "The constructed sandwich immunosensor could detect the cancer marker alpha fetoprotein (AFP) of primary liver cancer in the wide linear range of 0.1 pg/mL to 50 ng/mL, demonstrating good application prospects." (PMID 37754082, 2023). "Clinical characteristics such as biochemical and tumor biomarkers also play an important role in HCC diagnosis and prognosis, with the MTM-HCC being associated with a higher Barcelona Clinical Liver Cancer (BCLC) stage, poor histologic differentiation and higher serum alpha-fetoprotein (AFP)." (PMID 37197418, 2023). "Serum AFP ≥ 400 ng/mL is highly regarded as liver cancer, excluding pregnancy, chronic or active liver disease, germ gland embryogenic tumor and digestive tract tumor, we then analyzed the correlation between EXOSCs and AFP (400 ng/mL)." (PMID 36293016, 2022). "The high levels of AFP in the blood of an individual may be a sign of liver failure, damage, or liver cancer." (PMID 35592283, 2022). "In a randomized study including approximately 18,000 people in Shanghai, the group that underwent ultrasound and alpha-fetoprotein tests at 6-month intervals had a higher rate of detection of early liver cancer (<5 cm in size) compared to that of the control (45.3% vs. 0%)." (PMID 36142000, 2022). "According to χ2 tests, except for gemcitabine, there was a significant correlation between AFP and the three combination regimens (L-OHP + EPI + irinotecan + 5-FU, L-OHP + irinotecan + EPI, and L-OHP + EPI), with AFP-positive liver cancer cells being more sensitive than AFP-negative cells." (PMID 35127582, 2022). "The current biomarker commonly used to screen for liver cancer is AFP." (PMID 36096917, 2022). "IgM-free AIM is produced by macrophages, whereas DCP and AFP are produced by liver cancer cells; therefore, a combination assay of IgM-free AIM with AFP or DCP may be useful for HCC diagnosis." (PMID 34981443, 2022). "Understanding the clinical pathologic characteristics of liver cancer patients with low and high serum AFP could be helpful for clinical management and prognostication of this deadly disease." (PMID 35461226, 2022). "The liver cancer model was verified six weeks later by analyzing serum AFP levels." (PMID 35251971, 2022). "In liver cancer cells that secrete alpha-fetoprotein (AFP), miR-675 targets Twist1 and Rb1 to activate the expression of the epithelial marker gene CDH1 and inhibits the expression of the mesenchymal marker gene Vim to reduce the invasive ability of HCC and block EMT." (PMID 35805066, 2022). "Therefore, AFP has the problem of low sensitivity and specificity in the screening of liver cancer, and new serological indicators are needed to supplement the deficiency of AFP." (PMID 36523478, 2022). "The serum AFP is considered a tumor marker for liver cancer." (PMID 35624786, 2022). "Alpha-fetoprotein (AFP) is a potential liver cancer biomarker for the diagnosis of liver cancer." (PMID 36389169, 2022). "According to the results, we hypothesized that L-OHP and EPI exerted synergistic inhibitory effects in AFP-positive liver cancer cells." (PMID 35127582, 2022).